ASS1 (argininosuccinate synthase 1)
Diseases named in the same sentence as ASS1 in open-access papers (continued):
Sharing a sentence is not in itself a finding about the gene and the disease.
tumor (continued). "In general, ASS1-proficient tumours have been considered to be unsuitable for arginine-deprivation therapy." (PMID 26972697, 2016). "The role of ASS1 in tumor biology has been confusing, with ASS1 thought to act either as a tumor suppressor or as pro-metastatic or carcinogenic." (PMID 26982031, 2016). "In the presentstudy, we examined the effect of ASS1 on tumor metastasis in only animmune-competent mouse model." (PMID 25928182, 2015). "Moreover, the presence of ASS1 in tumour cells correlated with a better prognosis in NSCLC patients, especially when cancer-associated fibroblasts (CAFs) did not express arginase-2 (ARG2)." (PMID 41154605, 2025). "Overall, the intricate regulation of ASS1 by the circadian clock underscores its pivotal role in synchronizing metabolic and physiological processes such as ureagenesis, vascular function, and tumor biology." (PMID 41295280, 2025). "In addition, a further 6.2% of tumors showed ASS1 expression in less than 10% of their tumor cells (ASS1 low)." (PMID 41300990, 2025). "As a result, ASS1 is widely regarded as a tumor suppressor gene." (PMID 41300990, 2025). "Thus, ASS1 expression is a critical metabolic determinant that modulates both tumor fitness and immune interactions within the TME." (PMID 41511309, 2025). "We and others have further shown that ASS1 expression confers metabolic plasticity, enabling tumors to withstand nutrient stress, including glucose deprivation, and correlates with poor prognosis across several tumor types." (PMID 41511309, 2025). "Downregulation of Argininosuccinate Synthetase-1 (ASS1) supports tumor progression." (PMID 41300990, 2025). "However, with LNP-CTNNB1 treatment, tumor cells begin to express Cyp2f2, Arg1, and Ass1 along with diminished expression of Cyp2e1, Cyp1a2, Oat and others." (PMID 40442146, 2025). "Interestingly, the effect of ASS1 knockout to promote tumor growth was largely abrogated by PHGDH knockout." (PMID 38710705, 2024). "Similarly, the increase in tumor weight induced by ASS1 knockout was largely abrogated by further knockout of PHGDH." (PMID 38710705, 2024). "Additionally, the therapeutic effective-ness of ADT is constrained by the concept of paracrine trophicity in tumors, specifically, the expression levels of enzymes like ASS1 in tumor cells, which can limit the therapy’s applicability." (PMID 39239650, 2024). "Silencing ASS1/ASL hindered primary tumor growth while encouraging metastasis." (PMID 39090094, 2024). "However, with LNP-CTNNB1 treatment, tumor cells begin to express zone 1 markers, including Cyp2f2, Arg1, and Ass1, while decreasing expression of zone 3 genes (e.g., Cyp2e1, Cyp1a2, and Oat)." (PMID 39711542, 2024). "Moreover, PHGDH knockout abolished the proliferation-promoting effect of ASS1 knockout in vitro and in vivo, which indicated that the tumor suppressor function of ASS1 greatly depends on PHGDH." (PMID 38710705, 2024). "Taken together, these results indicate that PHGDH may be associated with TNBC recurrence, that its protein expression is downregulated by ASS1, and it is inversely associated with ASS1 expression in TNBC tumor tissue." (PMID 38710705, 2024). "Thus, ASS1 acts as a metabolic tumor suppressor and is silenced in many tumor types, making the finding of PDAC cells synthesizing arginine initially surprising." (PMID 37254839, 2023). "We first analyzed the expression of ASS1 in different tumors and non-tumor tissues." (PMID 38053661, 2023). "Yet as a carcinogenic factor, ASS1 is found to be highly expressed in a few other tumours." (PMID 36978187, 2023). "However, studies have identified metabolic vulnerabilities, including the downregulation of ASS1 in patients with myxofibrosarcoma, which correlates with increased tumor grade and stage." (PMID 37445845, 2023). "Profiling tumor gene expression of ASS1 and OTC before treatment could predict tumor response to arginine depletion with arginine-depleting enzymes." (PMID 37445845, 2023).
tumor (continued). "From the perspective of the tumour cell, resistance may be mediated via ASS1 upregulation, autophagy, and stromal cell refueling of arginine or its precursor argininosuccinate." (PMID 36903394, 2023). "The gene changes of ASS1 in different tumor samples of the TCGA were analyzed." (PMID 38053661, 2023). "Interestingly, ASS-1 protein and mRNA levels have recently been shown to be dependent on BRCA-associated protein 1 (BAP1) levels in MPM cells and tumours." (PMID 39516654, 2023). "Therefore, ASS1 downregulation influences NO metabolism and promotes tumor cell survival and proliferation via mitigation of cytotoxic effects of NO accumulation." (PMID 35910381, 2022). "In other words, it depends on the expression of ASS1 in tumor cells." (PMID 35898872, 2022). "Similarly, lncRNA 00312 attenuates tumor proliferation and invasion by functioning as a competitive endogenous RNA binding to miR34a-5p, making miR34a-5p unable binding to ASS1 to reduce ASS1 expression." (PMID 35910381, 2022). "Epigenetic silencing of ASS1 can stimulate tumor cell proliferation and migration." (PMID 35898872, 2022). "In preclinical studies, overexpression of ASS1 inhibited tumor growth." (PMID 35898872, 2022). "Likewise, depletion of arginine using pegylated arginine deaminase resulted in cell death in vitro and tumor regression in orthotopic xenograft models, whereas ASS1-expressing GBM cells were unaffected." (PMID 35898872, 2022). "Notably, recent studies deepened our insights into the role of ASS1 as a novel tumor suppressive character." (PMID 35674458, 2022). "ASS1 loss not only confers tumor cells with lack of tumor suppressor functions but also endows tumor cells to be more reliant on arginine supplement." (PMID 35910381, 2022). "Tumour rebiopsies at progression revealed ASS1 re‐expression as an escape mechanism." (PMID 35466524, 2022). "Moreover, ASS1 overexpression effectively improves the anti-tumor effect of chemotherapy by activating the PERK/eIF2α/ATF4/CHOP axis." (PMID 35910381, 2022). "Importantly, most treatment strategies focus on the effect of arginine starvation while neglecting the tumor suppressor effect of ASS1." (PMID 35674458, 2022). "Our study indicated for the first time that knockdown of PGAM1 could reconstruct the expression of ASS1 in BC cells, resulting in a decrease in tumor growth and exerting antitumor effects via cAMP/AMPK/CEBPB axis." (PMID 35674458, 2022). "It is gradually recognized that ASS1 play different role according to different tumor types." (PMID 35910381, 2022). "Moreover, we assessed the expression of PGAM1 and ASS1 in tumor tissues of these four groups collected at the end of the experiment by IHC." (PMID 35674458, 2022). "Besides, we outline how ASS1 affects metabolic regulation and tumor progression and further discuss the role of ASS1 in arginine deprivation therapy." (PMID 35910381, 2022). "Here, we revealed that silencing of PGAM1 could reconstruct the expression of ASS1 in BC cells to exert tumor‐suppressive effects." (PMID 35674458, 2022). "Downregulation of ASS1 has been found to play a tumor suppressor role in multiple malignancies." (PMID 35910381, 2022). "Moreover, high levels of argininosuccinate synthase 1 (ASS1) induce tumor growth and aggressiveness by elevating ARG amounts for NO synthesis." (PMID 36221263, 2022). "These tumor cells can synthesize arginine from citrulline by upregulating ASS1." (PMID 35898872, 2022). "Emphasis should be placed on personalizing treatment according to the ASS1 status of the tumor." (PMID 33979616, 2021). "In conclusion, loss of epithelial Ass1 does not affect epithelial transformation nor tumor progression after acute loss of both Apc alleles nor adenomagenesis in Apc heterozygous epithelium in vivo." (PMID 34599156, 2021).
tumor (continued). "As the importance of repressing mitochondrial ARG2 as a metabolic tumor suppressor in ccRCC has been established, we now focused on the cytosolic urea cycle enzymes ASS1 and ASL that convert citrulline and aspartate to arginine and fumarate via argininosuccinate." (PMID 34861885, 2021). "In addition, recent reports that ASS1 has other tumor suppressor functions such as inhibiting AKT activity." (PMID 34298755, 2021). "Importantly, overexpression of ASS1 in MDA-MB-231 cells significantly inhibited xenograft tumor development in mouse models." (PMID 33859183, 2021). "However, our work, as well as that of others, demonstrates that tumor and T cells can import citrulline and use it as an arginine substitute in vitro (when ASS1 is expressed)." (PMID 33979616, 2021). "Targeted inhibition of ASS1, or adoptive T cell therapy to induce ASS1 expression in patient immune cells, could reduce the tumor proliferative advantage." (PMID 33979616, 2021). "PEGylated arginine deiminase (ADI-PEG 20) has been applied to clinical anti-tumor therapy of HCC, melanoma and other ASS1-deficient cancers by depleting the external supply of arginine, which has also been shown to affect the hypoxia-induced processes by inhibiting HIF signal." (PMID 34858835, 2021). "Moreover, TCGA data analysis also revealed a prominent ASS1 downregulation in tumour samples from human GBM patients compared to normal brain tissue." (PMID 33809510, 2021). "ASS1 has been shown to repress Akt activities and behaves as a tumor suppressor." (PMID 34298755, 2021). "On the one hand, arginase itself can effectively starve ASS1-low tumor cells to death." (PMID 34298755, 2021). "Several studies focused on various tumors have shown that ASS1 may have a tumor suppressor function." (PMID 34447409, 2021). "In addition, several tumor types have been shown to downregulate ASS-1 expression, becoming auxotrophic for arginine." (PMID 31795337, 2019). "In addition, several tumor types have been shown to lack ASS-1 expression rendering them completely auxotrophic for arginine." (PMID 31795337, 2019). "To dissect the mechanisms underlying AR’s promotion of RCC cell proliferation, we focused on the ASS1, as recent studies have indicated that decreased ASS1 activity might lead to an increase in the tumor growth." (PMID 31000693, 2019). "Co-expression of AR with pseudogene ASS1P3 could block its suppression likely by inhibiting interaction between miR-34a-5p and ASS1P3, thus releasing the former to suppress ASS1 to promote the tumor growth." (PMID 31000693, 2019). "The pegylated recombinant arginine (Arg) deiminase ADI-PEG20 (hereafter ADI will be used) has been in clinical trials against multiple tumor types, because expression of argininosuccinate synthetase 1 (ASS1), the rate-limiting enzyme for the biosynthesis of Arg, is silenced." (PMID 28883660, 2017). "Here, we present a novel pathological role of ASS1 in tumor cells." (PMID 28358054, 2017). "In addition, DEPTOR expression levels were lower at the tumor invasive front than in the tumor center, which was similar to the expression pattern of ASS1." (PMID 28358054, 2017). "In such conditions, tumor cells with decreased ASS1 expression near the stroma may be attracted to arginine and invade ahead of other ASS1-expressing tumor cells." (PMID 28358054, 2017). "In the context of the in vivo tumor microenvironment, the ASS1 expression levels of each tumor cell may correlate with its invasion capability in response to changes in arginine concentration within the tumor microenvironment." (PMID 28358054, 2017).
tumor (continued). "Alternatively, neoadjuvant therapy might apply a selection pressure on tumor cells; with those express low ASS1 (more aggressive phenotype and more resistant to therapy) survive." (PMID 28187218, 2017). "The observation clearly indicates an enhanced uptake of arginine and citrulline by CRC cells and implies that this tumor entity might be more sensitive to arginine deprivation than expected from the ASS1 profile." (PMID 27689335, 2016). "If so, then techniques to suppress ASS1 could improve response to chemotherapy and would also render the tumor vulnerable to arginine depletion techniques, such as ADI-PEG20." (PMID 26982031, 2016). "Our data thus suggest that the combination of arginine starvation with canavanine treatment and irradiation may provide a strategy of clinical potential for treating tumor types with inducible ASS1 expression." (PMID 27689335, 2016). "This combined with the fact that hypoxic regions have a limited blood and nutrient supply, led us to hypothesise that arginine-deprivation therapy may be useful in targeting hypoxic-cancer cells, even in ASS1-expressing tumours." (PMID 26972697, 2016). "How sensitive individual cancers are to ADI-PEG20 will likely be influenced by the actual level of ASS1 activity, but our results imply that ADI-PEG20 could be clinically effective in tumours deemed ASS1-positive, by targeting hypoxic regions." (PMID 26972697, 2016). "In all 176 tumor samples, ASS1 protein was expressed in 87 (50%; more than 1+)." (PMID 26982031, 2016). "ASS1-expression was also reduced in ADI-PEG20-treated tumours with little effect seen on ASL." (PMID 26972697, 2016). "In paired samples, ASS1 was elevated in tumor compared to adjacent normal tissues." (PMID 26982031, 2016). "The absence of ASS1 expression was associated with increased angiogenesis, suggesting that ASS1 deficiency may contribute to tumour progression." (PMID 41154605, 2025). "In addition to directly regulating the expression of CD47, MYC may further help tumor cells escape phagocytosis by regulating the expression of argininosuccinate synthetase 1 (ASS1), a key enzyme in arginine biosynthesis." (PMID 40732268, 2025). "Additionally, an ASS1 increase in ECs has been observed in tumor contexts, including breast cancer." (PMID 41295280, 2025). "Interestingly, ASS1 is downregulated in certain tumor entities." (PMID 41300990, 2025). "These trials have highlighted the heterogeneous expression of ASS1 frequently observed suggesting that, even if the majority of tumor cells are ASS1-ve and therefore sensitive to arginine deprivation therapy, ASS1+ve cells may survive and proliferate upon ADI-PEG20 treatment." (PMID 39758821, 2025). "Additionally, ASS1, a mitochondrial metabolic enzyme, also reflects the activity of tumor cells." (PMID 39991825, 2025). "Importantly, the tumor suppressive effects of ASS1 were strongly abrogated by PHGDH knockout." (PMID 38710705, 2024). "Based on the negative correlation between the level of arginine uptake by tumor cells and the degree of ASS1 expression, the development of arginine metabolic molecular tracers can clarify the relationship between arginine metabolic level, ASS1 expression, tumor growth, and treatment time." (PMID 37895948, 2023). "Higher ASS1 expression level was correlated with poorer prognosis, indicating that the production of arginine could relief the arginine deficiency in tumor but may not be able to improve prognosis." (PMID 37214463, 2023). "Notably, upregulation of argininosuccinate 1 synthase (ASS1), an enzyme essential for cellular synthesis of arginine and its downstream metabolites, was identified in BAP1w-/KO cells and in BAP1-deficient MPM cells or tumor samples." (PMID 36669126, 2023). "Therefore, ASS1 expression levels in tumor tissues may serve as a predictive biomarker in the selection of patients who are more likely to benefit from arginine deprivation therapy." (PMID 37445845, 2023).
tumor (continued). "We found that loss of Ass1 did not affect tumor growth despite low levels of arginine in the TME." (PMID 37254839, 2023). "In addition, combination of ASS1 activators with anti-tumor drugs like chemotherapy and TKIs could augment the anti-tumor effect of traditional regimens." (PMID 35910381, 2022). "Besides, it has also been demonstrated that ASS1 may function as a tumor suppressor via metabolism–independent mechanism." (PMID 35910381, 2022). "Down-regulation or even loss of ASS1 and ASL that required for arginine synthesis from aspartate causes arginine-dependency; The expression of ASNS controls de novo asparagine synthesis and modulates tumor cell sensitivity to ASNase treatment mediated asparagine depletion." (PMID 35178349, 2022). "In accordance, silencing of ASS1 in BC could restore tumor growth in vitro and in vivo." (PMID 35674458, 2022). "Thus, our results establish spinosyn A and its derivative LM-2I as potent ASS1 enzymatic activator and tumor inhibitor, which provides a therapeutic avenue for tumors with low ASS1 expression and for those non-tumor diseases caused by down-regulation of ASS1." (PMID 33859183, 2021). "Low ASS1 expression was significantly correlated with high-grade histology (p = 0.016), but showed no further significant correlations with gender (p = 0.609), age (p = 0.150), tumor size (p = 0.489), margin status (p = 0.274), AJCC stage (p = 1.00) or lymph node status (p = 1.00)." (PMID 31903153, 2020). "Additionally, some parts of a heterogeneous tumor may express higher levels of ASS1 than the rest and be resistant from the start of treatment." (PMID 35582579, 2019). "However, ASS1 expression completely disappeared in relapsed tumor #4." (PMID 29094484, 2017). "Thus, our findings provide novel evidence for the importance of ASS1 in the migration/invasion capability of tumor cells, which might be helpful for understanding the pathological significance of arginine metabolism in tumor cells." (PMID 28358054, 2017). "The cells' ability to form 3-D multicellular tumor spheroids as an in vitro assay of intermediate complexity between standard monolayer culture and in vivo experiments turned out to be of particular interest as both cell lines showed enhanced ASS1 protein expression when grown in a 3-D environment." (PMID 27689335, 2016). "We speculate that ASS1 upregulation is in response to an increased need or decreased supply of arginine in 3D and in the tumor and would be a logical step in promoting survival of the tumor cells." (PMID 26982031, 2016). "Therefore, we used clone 2C10 ASS1 antibody for detecting ASS1 protein in spheroids and in tumor." (PMID 26982031, 2016). "ASS1 transcription is governed by many mechanisms and may depend on tumor cell types." (PMID 26771234, 2016). "Since ASS1 is the rate-limiting enzyme in arginine synthesis, its reduction impairs arginine synthesis in CRC cells, ultimately inhibiting tumor proliferation and migration." (PMID 41304979, 2025). "Conversely, reduced expression of ASS1 and ASL, leading to arginine deprivation, can trigger tumor cell death through mechanisms such as autophagy and apoptosis." (PMID 40535116, 2025). "Western blotting further validated a marked decrease in ASS1 protein levels and a concomitant upregulation of CAD expression in tumor tissues derived from the sh‐CD2 group." (PMID 40859981, 2025). "An in-depth survey of the expression levels in urea cycle enzymes also revealed that ASS1 and ASL were both upregulated in the primary tumor relative to the metastatic site." (PMID 39920310, 2025). "Argininosuccinate synthetase 1 (ASS1) expression and arginine availability are key metabolic determinants that influence tumor fitness and regulate immune interactions within the tumor microenvironment (TME)." (PMID 41511309, 2025).